MTOR (mechanistic target of rapamycin kinase)
Diseases named in the same sentence as MTOR in open-access papers (continued):
Sharing a sentence is not in itself a finding about the gene and the disease.
skin cancer (continued). "Upregulation of proteins in Ras/Raf/ERK and PI3K/AKT/mTOR pathways, MAPK (p38) and proto-oncogene (Src) as well as loss of tumor suppressor function (PTEN) have been implicated in several cancers including skin cancer." (PMID 31481122, 2019). "Modulation of these genes eventually promotes cell apoptosis in the skin tumor cells via inhibition of PI3K/AKT/mTOR signaling pathway in vivo." (PMID 31481122, 2019). "As in other organ types, skin cancers are the most frequent type of neoplasms after heart transplantation and use of mTOR inhibition appears to delay their recurrence." (PMID 27807479, 2016). "Nonetheless, the switch from calcineurin inhibitor to mTOR inhibitor did have a positive clinically significant effect on skin cancer development in this study." (PMID 25699174, 2015). "It should be mentioned that other trials have investigated the effect of mTOR inhibitors on development of skin cancer in transplant recipients, including a small randomised single-centre German study published by Salgo and colleagues." (PMID 25699174, 2015). "To date, alterations of the Akt/mTOR pathway have been observed in numerous types of carcinomas, but little has been reported about Akt/mTOR signaling in skin tumors." (PMID 20346172, 2010). "Current pharmacologic therapies to prevent occurrence of skin cancers include retinoid therapy, nicotinamide and the modulation of immunosuppression by converting from calcineurin inhibitors to mammalian target of rapamycin (mTOR) pathway inhibitors." (PMID 38323070, 2024). "Moreover, chrysin can potentially be a naturally derived adjuvant for the treatment of skin cancer, as it inhibits mTOR/S6K." (PMID 35884773, 2022). "Compared to normal skin, skin tumor tissues contain significantly elevated levels of phosphorylated mTOR and the downstream effectors S6K, 4E-BP1, and AKT (Ser473), which are implicated in increased cell proliferation, tumorigenesis, and resistance to apoptosis." (PMID 35938153, 2022). "Of note, PI3K/AKT/mTOR signaling has been described to be involved in resistance to specific inhibitors classically employed in NMSCs, due to the intricate crosstalk between different pathways in these skin cancers." (PMID 33996865, 2021). "It is ubiquitously known, overexpression of ERK, AKT, mTOR, p38 and proto-oncogene (Src) as well as the loss of tumor suppressor function (PTEN) proteins have been implicated in wide number of cancers in human including skin cancer." (PMID 31481122, 2019). "Given that the PI3K/Akt/mTOR signaling plays a crucial role in skin cancers, targeting this pathway with therapeutic nature-derived bioactive phytochemicals, biologic molecules, and synthetic small molecules alone or in various combinations is a promising strategy to treat skin cancers." (PMID 31370278, 2019). "Below, we summarize the relevance of the PI3K/Akt/mTOR pathways and the effector molecules in diverse skin cancers and discuss the mechanistic role of several synthetic molecules and dietary phytochemicals in inhibiting these pathways as potential therapeutic approaches." (PMID 31370278, 2019). "mTOR inhibitors have anti-viral effects and this may also account for their specific anti-skin cancer effect." (PMID 30473931, 2018). "Most of the beneficial effects of mTOR inhibitors on cancer were from the reduction of skin cancer." (PMID 30473931, 2018). "So far studies focusing on mTOR in the skin were limited to skin cancer and the role of mTORC1." (PMID 27486771, 2016). "Here, the problem of post-transplant skin cancer will be briefly reviewed, along with the possible mechanisms contributing to this problem, followed by an overview of the relevant clinical trial results using mTOR inhibitors." (PMID 25699174, 2015). "Therefore, in light of the high skin cancer incidence in transplant recipients, it follows that clinical trials have been conducted to determine if mTOR inhibitors can significantly reduce these post-transplant skin malignancies." (PMID 25699174, 2015).
skin cancer (continued). "The basic research to better understand this phenomenon continues to evolve at a steady pace, but in the meantime, clinical trials in transplant recipients already indicate that skin cancer can be reduced by substitution of calcineurin inhibitors with mTOR inhibitors." (PMID 25699174, 2015). "Particularly relevant for the topic of skin cancers in transplant recipients may be the recently discovered potential anti-viral effects of mTOR inhibitors." (PMID 25699174, 2015). "While this is not meant to be a full review of anti-tumour mechanisms potentially involved, it is worth pointing out some of the key roles of the mTOR pathway that could impact skin cancer development." (PMID 25699174, 2015). "Thus, this novel mTOR activator might be further tested as a promising strategy for skin cancer prevention." (PMID 28061443, 2017). "Finally, a study showing decreased expression of the TSC2 gene product, tuberin, in sporadic squamous and basal cell carcinomas suggests that mTOR inhibitors may be useful in treating these common skin cancers as well." (PMID 18226258, 2008). "On the other hand, skin tumors were enriched for the certain arms of the GNAQ signaling cascade, namely PI3K/AKT/MTOR signaling and RHO GTPases activating formins." (PMID 40950146, 2025). "UVB is reported to activate mTOR signaling, it plays a role in the development of skin cancer, but activated AMPK can inhibit mTOR activity." (PMID 33841160, 2021). "In the primary skin cancer model group, compared with control group, protein expressions of ki67, AKT, p-AKT, mTOR, p-mTOR, and HKII were all significantly increased." (PMID 33143000, 2020). "The results of this study showed that IQ exhibits an anti-proliferative property against SK-MEL-2 human skin cancer cells by downregulating the expression of phosphorylated PI3K, AKT and mTOR signaling proteins." (PMID 33260329, 2020). "Therefore, mTOR inhibitors could be a “game changer” to reduce the problem of post-transplantation skin cancer, but more research will be necessary to optimise clinical protocols that will be widely acceptable for high-risk patients that can benefit from this general strategy." (PMID 25699174, 2015). "However, over the past few years, evidence has emerged to suggest that one class of immunosuppressants, mammalian target of rapamycin (mTOR) inhibitors, could potentially inhibit skin tumour formation through a number of mechanisms that are still being studied intensively today." (PMID 25699174, 2015). "Studies have shown that decreasing the expression of HOXA11-AS in skin cancer cells may inhibit the proliferation, migration, and invasion of skin cancer cells by inhibiting the PI3K/AKT/mTOR signaling pathway." (PMID 35706412, 2022). "A provocative conclusion to this finding is that mTOR inhibitors delay, but do not prevent, skin cancers in these patients; a longer-term follow-up would be necessary to begin to address this issue." (PMID 25699174, 2015). "Apart from the experimental and theoretical view towards reducing skin cancer in organ transplant recipients with mTOR inhibitors, the first clinical trials with this aim have now been published." (PMID 25699174, 2015). "Moreover, other treatment strategies against MCC and other skin cancers are currently under investigation, including PI3K/mTOR inhibitors, domatinostat, adoptive cell therapy, and next-generation immune checkpoint inhibitors, such as anti-TIM-3, anti-TIGIT, and anti-LAD-3." (PMID 38793784, 2024). "A mammalian target of rapamycin (mTOR) inhibitor was commenced post-LT in 23/158 patients (14.6%): 16 prophylactically before development of recurrent HCC, three after diagnosis of recurrent HCC, and four for reasons unrelated to HCC (two for skin cancers, two for renal function preservation)." (PMID 36387254, 2022).
skin cancer (continued). "A recent meta-analysis in non-renal transplant recipients indicates that mTOR inhibitors may prevent second NMSC development but do not influence the development of the first skin cancer." (PMID 35505648, 2022). "The specific anti-cancer effect of mTOR inhibitors on skin cancer could not be explained in our study." (PMID 30473931, 2018). "Notably, however, patients given mTOR inhibition had a lower rate of skin cancer recurrence (p = 0.020) and lower mortality related to nonskin malignancies (p < 0.001)." (PMID 27807479, 2016).
Anxiety (58 papers, 2013 to 2025). Intense feelings of nervousness, tension, or panic often arise in response to interpersonal stresses. "For example, experimental data demonstrated that immunosuppressive drugs, such as the mechanistic target of rapamycin (mTOR) inhibitor rapamycin, can cause anxiety- and depressive-like behaviors in rodents." (PMID 41141866, 2025). "In the multivariate regression, the 11–17 years age group (1.67) and presence of anxiety (1.57), angiomyolipoma (1.51), and renal cysts (1.33) were significantly associated with the higher use of topical mTOR inhibitors." (PMID 36104799, 2022). "Significantly higher use of topical mTOR inhibitor was associated with the 11–17 years age group (OR, 1.67), anxiety (1.57), angiomyolipoma (1.51), and renal cysts (1.33)." (PMID 36104799, 2022). "Conversely, chronic inhibition of mTOR signaling is associated with decreased anxiety, improved learning and memory in animal models." (PMID 34381067, 2021). "The neurovascular enhancements by mTOR inhibition were associated with preserved white matter integrity and long-term memory, and reduced anxiety in aging mice." (PMID 29703936, 2018). "In this sense, although the reduction of BDNF, mTOR pathway activation has been associated to an increased anxiety-like behavior, other hippocampal neural markers might be correlated with the lower anxiety elicited by female MMP-9 OE mice." (PMID 40405318, 2025). "Arguably, the aberrant stimulation of MAPKs, FADD, and Akt/mTOR signaling pathways may rather contribute to stress-mediated changes in gene expression profiles and the subsequent neuroadaptations underlying the anxiety-like behavioral responses." (PMID 36768626, 2023). "Our own data, directly testing the involvement of S6K1, contradict this hypothesis and strongly suggest that anxiety induced by mTOR inhibitors can indeed be linked to an inhibition of the mTORC1 pathway." (PMID 33723223, 2021). "P38-MAPK, ↓ERK, Akt/mTOR → ↓neurons → anxiety, compulsive-like behaviors, and decreased activity levels." (PMID 39851502, 2025). "Within the CNS, mTOR signaling in microglia and neurons regulates neuroinflammation, synaptic maintenance, plasticity, and neurotransmission, a process relevant to anxiety, mood, and psychotic symptoms." (PMID 41462744, 2025). "Unique from TBI, dysfunction of the Akt/mTOR pathway has been observed to mediate anxiety following ischemic stroke, while increased expression of caspases 3, 8, and 9 in the hypothalamus, prefrontal cortex, and hippocampus mediate the presentation of PSD." (PMID 39851502, 2025). "In our previous study, curcumin, a diet-derived mTOR inhibitor has been shown to effectively mitigate learning and memory deficits and anxiety-like behavior in Tsc2+/− mice via inhibiting astroglial proliferation." (PMID 38296969, 2024). "Presently, our understanding of the mechanisms of NAc-PFC mTOR phosphorylation in the context of anxiety-related phenotypes is not well understood." (PMID 37702237, 2024). "Previous studies have shown that genetic removal of S6K1 in mice increases anxiety‐like behavior, and these results provide a basis for understanding reports of anxiety following mTOR inhibitor treatment." (PMID 37736829, 2024). "In one word, endurance training activates the brain mTOR pathway, which prevents demyelination and anxiety-like behaviors in CRS-treated mice." (PMID 36658152, 2023). "Fourteen-day treadmill exercise effectively prevented the anxiety phenotypes via potentiating mPFC neurons, which were dependent on cell-autonomous activation of the mTOR pathway." (PMID 36658152, 2023). "Thioridazine, a potent anti-psychotic and anti-anxiety agent, was specifically demonstrated to act against OC, possibly by targeting the mTOR pathway." (PMID 34224310, 2021). "Hyperactivity of the mTOR pathway (through PTEN knockout) has been shown to reduce anxiety-like behavior in the EPM." (PMID 34611610, 2021).
Anxiety (continued). "Collectively, these results provide grounds for the understanding of anxiety reports after treatments with mTOR inhibitors and will be critical for developing novel compounds targeting anxiety." (PMID 33723223, 2021). "We examined the role of mTOR knockdown in mPFC on depressive- and anxiety-like behavior by a single unilateral intracerebral infusion selectively into the IL or PrL cortices." (PMID 34445375, 2021). "Similar effects have been reported for genetically modified mice with autistic-like behavior, showing that mTOR inhibition attenuated anxiety, hyperexcitability, abnormal social interaction, repetitive behavior and vocalizations of the mice." (PMID 27829242, 2016). "Preclinical mouse models of Rett syndrome support this concept, as treatment of adult animals with mTOR-activating IGF-1 reduced anxiety levels and increased exploratory behaviors, suggesting that targeting mTOR can have an effect outside of the fetal developmental window." (PMID 38525876, 2024). "PTEN deletion in animal models leads to hyperactivation of the PI3K/Akt/mTOR signaling pathway in the hippocampal regions resulting in long-term alterations in social behaviors, repetitive behavior, and anxiety similar to autistic phenotypes establishing a role of mTOR pathway in ASD." (PMID 36838876, 2023). "Increased release of BDNF and enhanced TrkB signaling may be responsible for the induction of PI3K/Akt/mTOR and favorable effects on inflammation, apoptosis, anxiety-related behavior, and cognitive improvement seen in the present study after iTBS." (PMID 35656538, 2022). "First, the use of only one behavioral test to preliminarily analyze the state anxiety may hinder a wider effect on anxiety of the acute infusion of mTOR-siRNA in the IL cortex." (PMID 34445375, 2021). "The synaptic and behavioral phenotypes of Tanc2+/− mice implicate Tanc2 in the regulation of synaptic plasticity and behaviors, including LTP, learning and memory, hyperactivity, and anxiety-like behavior, all of which are reversed by rapamycin-dependent mTOR inhibition." (PMID 33976205, 2021). "Overall, our results demonstrate causality between mTOR expression in the IL cortex and depressive-like behaviors, but not in anxiety." (PMID 34445375, 2021). "The age-related increase in leucine and valine in B-GOS®-fed rats may activate the mTOR pathway which may contribute to maintaining low levels of anxiety long-term." (PMID 34611610, 2021). "The present study demonstrates the causal link between mTOR expression in the infralimbic cortex and depressive-like state, with no clear implication in state anxiety-like behavior, at least in the open-field test." (PMID 34445375, 2021). "Our data showed that EPO can increase hippocampal neurogenesis and promote anti-depressant and anti-anxiety-like effects, and that mTOR might be an important mediator in at least some of these outcomes." (PMID 24019878, 2013). "Notably, excessive activation of mTOR has been shown to interfere with cellular autophagy, leading to the accumulation of neurotoxic proteins within neurons, thereby exacerbating neurodegenerative changes and anxiety symptoms." (PMID 40509387, 2025). "On the basis of above findings, we hypothesize that chronic CORT treatment-induced depressive and anxiety like behaviour of mice is caused by dysregulation of AMPA receptor and subsequent mTOR signaling pathway and treatment with TSS might ameliorate these behavioural and molecular changes." (PMID 29609584, 2018). "Recent studies showed that chronic partial inhibition of mTOR by rapamycin reduce anxiety and depressive-like behavior in mice, possibly by stimulating major monoamine pathways, whereas intracerebroventricular infusion of rapamycin could inhibit the rapid antidepressant activity of ketamine." (PMID 27765060, 2016). "In addition to memory, we evaluated whether SE-induced mTOR hyperactivity altered locomotor activity and anxiety-like behaviors using the open field test." (PMID 23536771, 2013).
Anxiety (continued). "Our data provide evidence that TSS improves the depressive and anxiety like behavior via induction of AMPA receptor and subsequent mTOR signaling pathway which are involved in synaptogenesis." (PMID 29609584, 2018). "Together, these findings support the hypothesis that dysregulated microglial mTOR could sustain basal-ganglia inflammation contributing to sudden-onset OCD, tics, and anxiety." (PMID 41462744, 2025). "Therefore, JSO ameliorates anxiety-like behaviors by upregulating BDNF expression, suppressing hyperactivation of the PI3K/AKT/mTOR signaling pathway, and reducing the BAX/BCL-2 ratio, thereby enhancing neuronal survival and synaptic plasticity." (PMID 40509387, 2025). "Selective deletion of Fmr1 from forebrain excitatory neurons induces cellular, electrophysiological, and behavioral phenotypes in mice including increased mTOR/Akt phosphorylation and enhanced locomotor activity, but not anxiety-like behavior." (PMID 35768828, 2022). "Herein, we demonstrated that acute mTOR knockdown in the IL cortex, induced by the intracerebral administration of mTOR-siRNA, elicited a depressive-like state in mice, which was maintained for at least 48 h without affecting anxiety-like behavior." (PMID 34445375, 2021). "The infusion of mTOR-siRNAs in the PrL cortex did not produce changes in any of the tests used to evaluate depressive- or anxiety-like behaviors." (PMID 34445375, 2021).